SLAMF7 (SLAM family member 7)
Diseases named in the same sentence as SLAMF7 in open-access papers (continued):
Sharing a sentence is not in itself a finding about the gene and the disease.
myeloma (continued). "Targeting SLAMF7 has shown benefits in patients with MM because it functions through many pathways to enhance the growth of multiple myeloma cells." (PMID 34322356, 2021). "Precisely, a hemibody pair addressing CD38 and SLAMF7 redirects T cells against dual antigen-positive myeloma cells in vitro and in vivo, while sparing single antigen-positive bystanders." (PMID 33420283, 2021). "Ligation with elotuzumab, a humanized anti-SLAMF7 mAb approved to treat relapsing multiple myeloma, promotes NK cells degranulation and IFNγ production after 18h, whereas no significant NK cells activation was observed at 6h of stimulation in HC." (PMID 33828555, 2021). "This is in line with a previously reported case of EMD, where the malignant pleural effusion harbored myeloma cells with lower SLAMF7 expression than the bone marrow." (PMID 33575947, 2021). "Signaling lymphocytic activation molecule F7 (SLAMF7, also known as CS-1 or CD319) is a well-known target in multiple myeloma." (PMID 34572927, 2021). "SLAMF7 is highly expressed on multiple myeloma cells and more modestly expressed on NK cells and a subset of T cells." (PMID 34638271, 2021). "Based on the favorable co-expression of CD38 and SLAMF7 antigen at high levels on MM, we tested hemibodies in vivo using myeloma xenografts and human peripheral blood mononuclear cells (PBMCs) in a humanized immunodeficient NOD SCID Il2rg−/− (NSG) mouse model." (PMID 33420283, 2021). "The high level of SLAMF7 expression on myeloma cells prompted the development of elotuzumab, a humanized MAb that binds to SLAMF7." (PMID 32138182, 2020). "SLAMF7 is highly expressed in almost all patients with multiple myeloma, a malignant disease of plasma cells." (PMID 32487061, 2020). "It has previously been shown that cleaved Slamf7 promotes the growth of multiple myeloma and that inhibition of SLAMF7 blocks adhesion of multiple myeloma cells to bone marrow stromal cells." (PMID 32292352, 2020). "After 20 h of co-culture with myeloma cells, anti-SLAMF7 CAR T cells exerted antitumor activity, resulting in lysis of more than 90% of myeloma cells." (PMID 32316105, 2020). "Elotuzumab is a humanized anti-SLAMF7 (signaling-lymphocyte-activating molecule F7) monoclonal antibody that targets SLAMF7 on myeloma cells and can lead ADCC via CD16 on NK cells and ADCP by macrophages." (PMID 32231116, 2020). "They found that soluble SLAMF7 can bind surface SLAMF7 on myeloma cells, leading to activation of the SHP-2/ERK signaling pathways." (PMID 31842518, 2019). "The transmembrane glycoprotein CD38 and the immunoreceptor SLAMF7 are the targets of the two monoclonal antibodies currently approved for the treatment of multiple myeloma, daratumamab and eloztuzumab, respectively." (PMID 31231360, 2019). "Nowadays, another moAb, elotuzumab, has been approved in MM therapy targeting the SLAMF7 molecule expressed among normal and myeloma PCs, NK, and T cells." (PMID 31041312, 2019). "Signaling lymphocytic activation molecule family 7 (SLAMF7 or CS1) is a cell surface glycoprotein whose expression is essentially restricted to NK cells and both normal and abnormal plasma cells, with 95% of myeloma plasma cells being SLAMF7-positive." (PMID 31861548, 2019). "The SLAMF7 CAR T cells induced rapid cytolysis of primary myeloma cells from patients with untreated and RRMM." (PMID 31684964, 2019). "In NK cells, SLAMF7 self-ligation can enhance NK cell activity through adaptor protein EAT-2 recruitment, although the function and adaptor protein-mediated signaling of SLAMF7 in myeloma cells remain to be clarified." (PMID 31842518, 2019). "SLAMF7 is highly expressed by more than 97% of myeloma cells while its expression is restricted in normal cells." (PMID 29662641, 2018).
myeloma (continued). "Elo strongly promoted degranulation of NK cells that required integrity of the Fc domain and correlated with SLAMF7 expression level on the myeloma cells, thereby confirming that the main mechanism of action of Elo is NK cell-mediated ADCC." (PMID 30455698, 2018). "Elotuzumab is a humanized IgG1 monoclonal antibody targeting SLAMF7, which is highly expressed on myeloma cells, and the antibody is approved for the treatment of relapsed and/or refractory (RR) MM in combination with lenalidomide and dexamethasone." (PMID 30455698, 2018). "The expression of SLAMF7 is limited on myeloma and natural killer cells, which ensures minimal effects on healthy tissue." (PMID 30643823, 2018). "Further research is also clearly warranted to improve our minimal understanding of the impacts of Elo on anti-myeloma responses by SLAMF7-expressing monocytes, macrophages, and DC." (PMID 30455698, 2018). "The approval of the first two monoclonal antibodies targeting CD38 (daratumumab) and SLAMF7 (elotuzumab) in late 2015 for treating relapsed and refractory multiple myeloma (RRMM) was a critical advance for immunotherapies for multiple myeloma (MM)." (PMID 30147690, 2018). "Signaling Lymphocyte Activation Marker Family member 7 (SLAMF7) was found highly expressed on human plasma cells and corresponding myeloma cells." (PMID 30455698, 2018). "High SLAMF7 protein expression on the cell surface of multiple myeloma cell lines and patient myeloma cells spurred the development of monoclonal antibodies targeting SLAMF7 for the treatment of this cancer." (PMID 31548533, 2017). "Like other multiple myeloma antigens, i.e., SLAMF7, CD138, CD38, soluble BCMA was detected in the elevated levels in the serum samples of multiple myeloma when compared with normal donors." (PMID 31548533, 2017). "SLAMF7 is an established therapeutic target for multiple myeloma, and a monoclonal antibody (elotuzumab) targeting SLAMF7 can activate natural killer cells to selectively kill myeloma cells." (PMID 28211524, 2017). "Myeloma cells are also characterized by the expression of SLAMF7, a glycoprotein expressed in hematopoietic cells, such as NK or CD8+ T cells and overexpressed by MPCs." (PMID 28848556, 2017). "Despite early disappointments, monoclonal antibodies targeting CD38 (daratumumab) and signaling lymphocytic activation molecule F7 (SLAMF7) (elotuzumab) have become available for patients with multiple myeloma in the same year." (PMID 31548533, 2017). "Studies have shown that SLAMF7-mediated signaling is important for the interaction between myeloma cells and their adhesion to bone marrow stromal cells (BMSCs) and can activate ERK1/2, STAT3, and AKT pathways to promote survival." (PMID 27417553, 2016). "Elotuzumab also promotes cytotoxicity against SLAMF7-expressing myeloma cells by mechanisms other than ADCC, including direct activation of NK cells." (PMID 25287778, 2015). "The high expression of SLAMF7 in multiple myeloma made it an attractive therapeutic target." (PMID 41187703, 2026). "Hence, the SLAMF7 glycoprotein is a highly specific, biologically substantiated, and clinically proven target for cellular therapy in multiple myeloma." (PMID 40649828, 2025). "while targeting a non-specific antigen like SLAMF7 in myeloma has its limitations, such as the risk of off-target effects and potential resistance, it also offers opportunities for broader application and can be a valuable part of combination therapies." (PMID 38438559, 2024). "SLAMF7-mediated myeloma killing depends on NK cell-mediated ADCC." (PMID 38410372, 2024). "SLAMF7 has also been shown to be effective in improving survival when combined with lenalidomide and dexamethasone with the monoclonal antibody elotuzumab in patients with multiple myeloma." (PMID 38476238, 2024). "Additionally, the extracellular domain of SLAMF7 can be cleaved to form soluble SLAMF7 (sSLAMF7), a compound that facilitates myeloma cell growth." (PMID 38892379, 2024).
myeloma (continued). "Targeting transcriptional factors could lead to a decrease in the expression of SLAMF7 in multiple myeloma cells." (PMID 37754488, 2023). "The role of SLAMF7 in myeloma cell proliferation isn’t entirely clear yet." (PMID 37754488, 2023). "SLAMF7 is highly expressed in myeloma cells and plays an important role in the pathogenesis of MM." (PMID 37754488, 2023). "Besides its expression on myeloma cells, SLAMF7 is also present in immune cells, particularly in natural killer (NK) cells, where it serves as a costimulatory receptor to stimulate innate and adaptive immunity." (PMID 37190123, 2023). "SLAMF7 is important for myeloma cell interactions with bone marrow stromal cells." (PMID 37754488, 2023). "SLAMF7 expression is currently used as a marker for multiple myeloma and plasmablastic lymphomas." (PMID 37971257, 2023). "SLAMF7 has been regarded previously as a target for immunotherapy in multiple myeloma." (PMID 35659630, 2022). "SLAMF7 may serve as an indicator to identify CD8+ Tregs and anti-SLAMF7 antibodies that enhance anti-myeloma responses." (PMID 36176763, 2022). "SLAMF7 CAR-T cells demonstrated its anti-myeloma-killing effect in mouse models." (PMID 36261831, 2022). "Of note, none of the other 7 myeloma cell binding scFv phage antibodies showed reactivity to the CHO cell lines expressing MM antigens like BCMA, CD138 or SLAMF7, and might therefore recognize other, potentially novel antigens on myeloma cells." (PMID 35784366, 2022). "Additionally, myeloma plasma cells showed high expression levels of this receptor, making SLAMF7 an interesting therapeutic target for multiple myeloma patients." (PMID 33430210, 2021). "SLAMF7 is a homotypic receptor that plays a role for myeloma cell homing to the bone marrow niche." (PMID 33575947, 2021). "While CD38 and SLAMF7 were detected at high levels on the surface of virtually all myeloma cells even in heavily pretreated patients, we found heterogeneous BCMA expression with substantial inter- and intra-individual differences and the regular occurrence of BCMA-negative subpopulations." (PMID 33420283, 2021). "Thus, to investigate the expression of SLAMF7 on myeloma cells of EMD under therapeutic selection pressure, we screened our electronic database for patients with de novo EMD during elotuzumab treatment." (PMID 33575947, 2021). "In recent years, the introduction of monoclonal antibodies (mAbs) targeting CD38 and the signaling lymphocytic activation molecule family member 7 (SLAMF7) represents an important step towards the treatment of relapsed/refractory multiple myeloma (RRMM) patients." (PMID 32899714, 2020). "Antibody against SLAMF7 (high expression on multiple myeloma)." (PMID 32153582, 2020). "However, while treatment with SLAMF7 antibody and secondary crosslinker can induce varying levels of tyrosine phosphorylation of the receptor in different myeloma cell lines, SHIP-1 was only minimally tyrosine phosphorylated, if at all." (PMID 30455698, 2018). "Importantly, SLAMF7 expression was preserved on myeloma cells at significant levels upon relapse in most patients." (PMID 30455698, 2018). "In addition to plasma cells and myeloma cells, SLAMF7 is expressed in healthy donors on essentially all CD56dim NK cells, the majority of CD56bright NK cells, many CD56+ T cells, mature dendritic cells, and small subsets of CD4+ T cells and B cells." (PMID 30455698, 2018). "While the physiological function of SLAMF7 on plasma cells is still unknown, the high expression on myeloma cells raised interest as a therapeutic antibody target." (PMID 30455698, 2018). "The humanized anti-SLAMF7 monoclonal antibody elotuzumab has been developed and shown promising efficacy in phase 1 and 2 trials on patients with refractory and relapsed multiple myeloma." (PMID 29905534, 2018).
myeloma (continued). "The availability of two antibodies targeting distinct myeloma cell surface markers (SLAMF7 and CD38, respectively) provides an advantage that could be exploited in treating MM patients." (PMID 30455698, 2018). "Most advanced is the recruitment of innate immunity to kill myeloma cells by monoclonal antibodies targeting antigens either aberrantly expressed on myeloma cells (e.g. SLAMF7 -elotuzumab) or expressed on both, normal as well as malignant plasma cells (e.g. CD38 -daratumumab, isatuximab)." (PMID 29156688, 2017). "SLAMF7 plays an important role in the interaction between myeloma cells and BM stromal cells." (PMID 28848556, 2017). "A clinical phase I dose-escalation study in patients with relapsed/refractory MM demonstrated that elotuzumab had acceptable tolerability at doses sufficient to achieve biologically relevant serum concentrations and saturate SLAMF7 on myeloma cells in bone marrow." (PMID 25287778, 2015). "Elotuzumab is a humanized monoclonal antibody specific for signaling lymphocytic activation molecule-F7 (SLAMF7, also known as CS1, CD319, or CRACC) that enhances natural killer (NK) cell-mediated antibody-dependent cellular cytotoxicity (ADCC) of SLAMF7-expressing myeloma cells." (PMID 25287778, 2015). "Since the cell cycle plays a critical role in chemosensitivity for combination chemotherapy, we also investigated whether SLAMF7 knocking down could potentiate the activity of bortezomib, a proteasome inhibitor with significant activity in myeloma." (PMID 23900284, 2013). "As SLAMF7 is highly expressed in multiple myeloma cells and macrophages under conditions of bacterial infection, suppression of SLAMF7 may contribute to treatment failure in multiple myeloma patients and exacerbate hyperinflammatory responses to systemic bacterial infections." (PMID 40646691, 2025). "Furthermore, SLAMF7 is known to be a regulator of NK cell function, and in vitro studies have shown that elotuzumab binding to SLAMF7 on NK cells directly activates them, enhancing their cytotoxic activity against myeloma cells." (PMID 38143697, 2023). "Additionally, Elotuzumab is an anti-SLAMF7 monoclonal antibody that is FDA-approved for the treatment of multiple myeloma, raising the possibility that such drugs could also be used in the treatment of EBV-associated tumors with high SLAMF7 expression." (PMID 37971257, 2023). "Finally, elotuzumab is a moAb specifically directed against SLAMF7, a glycoprotein expressed on myeloma cells, able to promote the killing of myeloma cells, mainly through NK-mediated ADCC, as well as by preventing interactions between myeloma cells and BM stromal cells." (PMID 35563634, 2022). "SLAMF7 as a biomarker could also provide information on the progression of multiple myeloma." (PMID 36574434, 2022). "As the presence of the respective antigen is an obligatory prerequisite for efficient targeted therapy, we hypothesized that another reason for the observed inferior outcome data in our cohort could be reduced SLAMF7 expression on myeloma cells located outside the bone marrow niche." (PMID 33575947, 2021). "However, the downstream signaling network induced upon SLAMF7 activation in myeloma cells-and thus the functional relevance of SLAMF7 expression for the maintenance of the disease-remains unclear to date." (PMID 33575947, 2021). "Furthermore, a SB-engineered signaling lymphocytic activation molecule (SLAM) family member 7 (SLAMF7)-specific T cell product for treatment of patients suffering from multiple myeloma is currently under investigation in a phase I/II clinical trial CARAMBA-1 (NCT04499339; EU Horizon 2020 project)." (PMID 33807011, 2021). "Thus, we aimed to investigate SLAMF7 protein expression on myeloma cells at extramedullary sites." (PMID 33575947, 2021). "Second-line targets, such as SLAMF7, CD38, CD138, TACI, and APRIL, possess biological validity, high expression on myeloma cells, and proven therapeutic potential in preclinical and early clinical trials." (PMID 40649828, 2025).
myeloma (continued). "Together with the CD38-, SLAMF7-, and BCMA-focused platforms, talquetamab contributes to the emerging paradigm of multi-antigen, multi-platform immunotherapy in multiple myeloma, enabling more personalized and strategically layered treatment approaches." (PMID 41511330, 2025). "For example, CS1 (CD2 subset 1; also known as CD319, CRACC, or SLAMF7) forms a homodimer on both multiple myeloma cells and NK cells and is highly overexpressed in multiple myeloma." (PMID 41463154, 2025). "Most human myeloma cell lines tested exhibited higher CS1 cell surface and/or SLAMF7 mRNA expression compared to HEK293A cells." (PMID 40247106, 2025). "Combination therapy with anti-myeloma drugs, bortezomib, melphalan, panobinostat and pomalidomide, enhanced Ad[CE1A] efficacy, with melphalan upregulating SLAMF7, resulting in increased viral replication." (PMID 40247106, 2025). "In human myeloma cells, Ikaros zinc finger 1 (IKZF1) was identified as the pivotal transcriptional activator of SLAMF7; however, the murine SLAMF7 (mSLAMF7) promoter was found to be regulated by YY1 in B cells." (PMID 40247106, 2025). "In the context of Multiple Myeloma, notable antigens such as CD19, CD38, CD138, BCMA (B-cell Maturation Antigen), Kappa (κ) light chain, SLAMF7, NKG2D, and GPRC5D have been identified as effective targets for CAR T-cell therapy." (PMID 38438559, 2024). "As a consequence, there is increasing interest in combinatorial immunologically based strategies that employ BCMA with other validated myeloma targets, such as CD38, SLAMF7, and CD19 or with emerging viable targets like GPRC5D." (PMID 37958658, 2023). "SLAMF7, also known as CD319 and previously as CD2 subset 1, is a validated myeloma target bound by elotuzumab." (PMID 37111346, 2023). "O’Neal and colleagues developed and evaluated SLAMF7 CAR T cells targeting the V domain of SLAMF7 (Luc90-SLAMF7 CAR T) and demonstrated anti-myeloma killing in vitro and in vivo using two myeloma mouse models." (PMID 37251372, 2023). "SLAMF7, also known as CS1/CRACC/CD319, promotes myeloma cell proliferation and growth due to its upregulation and high expression in MM cells." (PMID 37754488, 2023). "Elotuzumab directly activates NK cells through both the SLAMF7 pathway and ADCC for the treatment of multiple myeloma (MM)." (PMID 35664074, 2022). "CD19, SDC1 (CD138), CD38, SLAMF7, and TNFRSF17 (BCMA) were selected for targeting multiple myeloma (MM)." (PMID 34975912, 2021). "Like SLAMF7, CD38 has been identified as a target for mAb to eliminate myeloma cells in patients with relapsing multiple myeloma with the use of anti-CD38 daratumumab." (PMID 33828555, 2021). "SLAMF7 CAR-T cells confer potent and consistent anti-myeloma activity in preclinical assays in vitro and in vivo." (PMID 33846552, 2021). "The clinical studies have identified several numbers of target antigens expressed on abnormal plasma cells in multiple myeloma, including CD19, CD38, CD138, SLAMF7, kappa light chain, B cell maturation antigen (BCMA), and SLAMF7." (PMID 33781320, 2021). "Given that SLAMF7 is a self-ligand, we cannot exclude that for extramedullary spread of single cells, e.g. into peritoneum, pleural cavity, or cerebrospinal fluid, accompanied by a disintegration of myeloma cell aggregates, SLAMF7 might become more dispensable for the persistence of the disease." (PMID 33575947, 2021). "Signaling lymphocyte activation molecule family 7 (SLAMF7, also known as CS-1, CD319, and CRACC) is a receptor of the CD2 family that is overexpressed on myeloma cells, subsets of natural killer (NK) cells, macrophages, and T cells." (PMID 33597728, 2021). "Clinical trials into targeting different myeloma antigens, such as B cell maturation antigen (BCMA), CD138, immunoglobulin light chains and CS1 glycoprotein antigen (SLAMF7) are ongoing." (PMID 32645977, 2020).